GATA4 (GATA binding protein 4)
Diseases named in the same sentence as GATA4 in open-access papers (continued):
Sharing a sentence is not in itself a finding about the gene and the disease.
myeloid leukemia (1 paper, 2015). A clonal proliferation of myeloid cells and their precursors in the bone marrow, peripheral blood, and spleen. "In this study, we have provided the first evidence of GATA4 methylation in two AML cell lines and pediatric myeloid leukemia samples." (PMID 26490736, 2015). "MSP and BGS analysis showed that the GATA4 gene promoter is hypermethylated in AML cells, such as the HL-60 and MV4-11 human myeloid leukemia cell lines." (PMID 26490736, 2015).
nasopharyngeal carcinoma (1 paper, 2022). A carcinoma arising from the nasopharyngeal epithelium. "For example, GATA4 has been shown to induce EMT in nasopharyngeal carcinoma cells, whereas it was found to induce MET in HCC cells." (PMID 34708244, 2022).
neuroblastoma (1 paper, 2009). Neuroblastoma (NB) is the most common solid, extracranial childhood tumor. "Together, these findings support the notion that GATA-4 is specifically upregulated in neuroblastoma pathogenesis instead of being expressed in progenitor cells of the developing sympathetic system." (PMID 19707195, 2009). "Taken together, GATA-4 expression appears to be a common feature of neuroblastoma with highest expression levels in MYCN-amplified tumours." (PMID 19707195, 2009). "In contrast, upregulation of GATA-4 appears to be a common feature of this malignancy and might contribute to neuroblastoma pathogenesis." (PMID 19707195, 2009). "Apparently, GATA-4 expression only arises during tumourigenesis of neuroblastoma, suggesting that it may have a role in the pathogenesis of neuroblastoma." (PMID 19707195, 2009). "Furthermore, we demonstrate nuclear GATA-4 protein expression in human neuroblastoma cells." (PMID 19707195, 2009). "It should be noted that we found significantly higher GATA-4 expression levels in the unfavourable subgroups of MYCN-amplified tumours and of neuroblastoma with unfavourable PAM prediction." (PMID 19707195, 2009). "Although FOG-2 is likely to interact with any GATA protein, our data obtained in neuroblastoma specimens suggest a predominant interaction with GATA-2 and/or GATA-3; in addition, the interaction between FOG-2 and GATA-4 could be disturbed." (PMID 19707195, 2009). "In contrast, the finding of GATA-4 expression in primary neuroblastoma, but not in cells of the developing nervous system, indicates its unique role in neuroblastoma pathogenesis." (PMID 19707195, 2009).
neuroendocrine carcinoma (1 paper, 2024). A malignant neuroendocrine neoplasm composed of cells containing secretory granules that stain positive for NSE and chromogranin. "Antibody array protein chip analysis of transcription factors in 3DiNET ORION cells revealed expression of several intracellular transcription factors involved in neuroendocrine cancer pathobiology—Snail, GATA4, FoxA2, Sox-2, PDX-1 and E-cadherin." (PMID 39103560, 2024). "Protein array analysis showed expression of multiple intracellular transcription factors involved in neuroendocrine cancer pathobiology—Snail, GATA4, FoxA2, Sox-2, PDX-1 and surface molecule (E-cadherin)." (PMID 39103560, 2024).
neuroendocrine tumor (1 paper, 2021). "In mouse neuroendocrine tumor derived cells, GATA4 increases insulinotropic polypeptide gene expression." (PMID 33865372, 2021).
oesophageal cancer (1 paper, 2016). "GATA4 is located at chromosome 8p, a chromosomal locus frequently deletedin multiple tumour types such as colorectal and oesophageal cancer (Refs 142, 143).Alternatively GATA4 can be downregulated via epigenetic silencing, such ashypoacetylation of histones H3 and H4 (Ref." (PMID 26953528, 2016).
Osteopenia (1 paper, 2023). Osteopenia is a term to define bone density that is not normal but also not as low as osteoporosis. "Conditional knockout (cKO) of Gata4 in osteoblast progenitors (using PRX1-CRE) causes osteopenia." (PMID 37754840, 2023).
ovary (1 paper, 2012). "The expression of GATA-4 and FOG-2, one of its modulators, was studied in pediatric Sex Cord-Stromal tumors of the ovary, in order to evaluate their potential role as diagnostic markers and prognostic factors." (PMID 23029311, 2012).
persistent Müllerian duct syndrome (1 paper, 2024). "A mutation inactivating the distal SF1 binding site on the AMH promoter causes persistent Müllerian duct syndrome (PMDS) due to ineffective interaction with NR5A1 and GATA4." (PMID 38785542, 2024).
prostate tumors (1 paper, 2024). "Compared to adjacent non-tumor tissues, GATA4 was significantly upregulated in prostate tumors from AA men (P < 0.05)." (PMID 38566104, 2024).
pulmonary hypertension (1 paper, 2018). Increased pressure within the pulmonary circulation due to lung or heart disorder. "In our previously studies, the RV GATA4 DNA binding activity was found to be increased in a rat model of pulmonary hypertension." (PMID 30096794, 2018). "However, this was not because of the post-translational activation of this protein, but due to increased gene transcription, since both protein and mRNA levels of GATA4 were also increased in response to pulmonary hypertension in the RV, but not in the LV." (PMID 30096794, 2018). "Further, annexin A1 gets degraded in the RV, but not in the LV, in response to pulmonary hypertension, indicating that the activation of CBF/NF-Y-dependent GATA4 gene transcription is through releasing the negative regulation by annexin A1." (PMID 30096794, 2018).
renal agenesis (1 paper, 2013). Renal agenesis (RA) is a form of renal tract malformation characterized by the complete absence of development of one or both kidneys (unilateral RA or bilateral RA respectively), accompanied by absent ureter(s). "We found that Frem1 and Gata4 interact genetically in the development of lung lobulation defects and that Frem1 and Slit3 interact genetically in the development of renal agenesis." (PMID 23536828, 2013). "These experiments reveal that Frem1 interacts genetically with Gata4 in the development of lung lobulation defects and with Slit3 in the development of renal agenesis." (PMID 23536828, 2013).
rhabdomyosarcoma (1 paper, 2023). A rare aggressive malignant mesenchymal neoplasm arising from skeletal muscle. "Overall, these results suggest that interactions of GATA4 with PRC2 components are important in rhabdomyosarcoma progression." (PMID 37664059, 2023). "A direct interaction between EZH2 and GATA4 was also observed in rhabdomyosarcoma, a type of soft tissue sarcoma that develops from muscle or fibrous tissue, and a rare type of sarcomas of the heart." (PMID 37664059, 2023).
right ventricular dysplasia (1 paper, 2020). "In the early stage of cardiac development, GATA4-deficient mice showed decreased myocardial proliferation, a lack of mesenchymal cells in the cardiac cushion, and right ventricular dysplasia and GATA4 deletion in the late stage showed double right ventricular outflow with myocardial thinning." (PMID 32380971, 2020).
seminoma (1 paper, 2021). A radiosensitive malignant germ cell tumor found in the testis (especially undescended), and extragonadal sites (anterior mediastinum and pineal gland). "In contrast, expression of proposed YST key factors could clearly be associated with YST tissues and YST‐containing mixed GCTs, but not with ECs or seminomas (except SOX17 and GATA4)." (PMID 33448076, 2021).
Sertoli cell tumor (1 paper, 2012). A sex cord-stromal tumor of the testis or the ovary. "High GATA-4 expression in tumoral cells was reported in a pediatric series of 1 testicular Sertoli cell tumor and 5 testicular Leydig cell tumors: this expression was higher in neoplastic cells than in normal adjacent Sertoli cells and Leydig cells of the same patients." (PMID 23029311, 2012).
Sertoli-Leydig cell tumor (1 paper, 2012). A sex cord-gonadal stromal tumor consists of leydig cells; sertoli cells; and fibroblasts in varying proportions and degree of differentiation. "Sertoli-Leydig cell tumors, which represent the more aggressive histotype, showed a higher expression of GATA-4, conversely to what detected in JGCTs." (PMID 23029311, 2012).
stable angina (1 paper, 2018). "In a previous clinical study, increased expression of specific cardiac markers (Nkx2-5, gata-4, and mef2c) in PBMNCs, and increased number of CD34+/CXCR4+ and CD34+/CD117+ stem cells in PB were observed in ST-elevated MI patients compared to patients with stable angina and healthy Controls." (PMID 30485279, 2018).
Stroke (1 paper, 2011). Sudden impairment of blood flow to a part of the brain due to occlusion or rupture of an artery to the brain. "We conclude that the common GATA4 variant S377G is relatively benign in terms of its participation in CHD and PFO/Stroke." (PMID 21673957, 2011). "In an initial study of Australian subjects, we observed a weak association between GATA4 S377G and PFO/Stroke relative to Caucasian controls in whom ASD and PFO had been excluded (OR = 2.16; p = 0.02)." (PMID 21673957, 2011). "Thus, the common GATA4 variant S377G is likely to be relatively benign in terms of its participation in CHD and PFO/Stroke." (PMID 21673957, 2011). "In our initial screen of 162 subjects (including 43 PFO/stroke, 9 incidental PFO with no stroke and 110 ASD subjects), all coding exons of the GATA4 gene were sequenced." (PMID 21673957, 2011).
testicular diseases (1 paper, 2012). "Moreover, the Gata4 mRNA, encoding a transcription factor of Sertoli cells that is increased in many testicular diseases in patients, was also clearly upregulated in Sertoli cells with heterozygous Cre expression." (PMID 22829911, 2012).
triple-negative breast carcinoma (1 paper, 2025). An invasive breast carcinoma which is negative for expression of estrogen receptor (ER), progesterone receptor (PR), and human epidermal growth factor receptor 2 (HER2). "The results of this study highlight the potential role of epigenetic regulation of ADIPOQ, GAS5, GATA4, and YAP1 in the molecular pathology of triple-negative breast cancer." (PMID 41226688, 2025).
Truncus arteriosus (1 paper, 2019). A single arterial trunk arises from the cardiac mass. "Gata4/Gata6 compound heterozygotes displayed persistent truncus arteriosus (PTA), a severe OFT defect caused by combined alignment and OFT septation defects." (PMID 31120883, 2019).
Wilms tumor (1 paper, 2016). An embryonal neoplasm characterized by the presence of epithelial, mesenchymal, and blastema components. "The mutation near Wilms tumor protein altered a Gata4 transcription factor binding site." (PMID 27756226, 2016).
yolk sac tumor (1 paper, 2012). A non-seminomatous malignant germ cell tumor composed of primitive germ cells. "This has already been suggested by Mannisto and colleagues who observed that in a series of yolk sac tumors the aggressive clinical behaviour was related to the higher activity of GATA-4 in the absence of FOG-2." (PMID 23029311, 2012).
tumor (94 papers, 2009 to 2025). "The strong association between GATA3 and GATA4 expression supports their potential synergistic role in tumor biology." (PMID 41303462, 2025). "Remarkably, we observed that Gata4-mediated tumor suppression was circumvented by loss of the adaptive immune system." (PMID 35017504, 2022). "In six of nine tumor types examined, loss of GATA4 was significantly associated with decreased abundance of specific immune-related transcript sets indicative of tumor-infiltrating cytotoxic CD8 T cells, CD4 T cells, and B cells." (PMID 35017504, 2022). "Recently, a potent tumour suppression mechanism has been associated with CD8+ T cells recruitment by the transcription factor GATA Binding Protein 4 (GATA4)." (PMID 35406451, 2022). "It has been reported GATA4 expression is associated with increased tumor size, metastasis, and a poor prognosis." (PMID 33648545, 2021). "Our study revealed a previously unnoticed tumor suppressor enhancing module and shed light on a therapeutic opportunity for GATA4 deficient HCC patients." (PMID 31903133, 2020). "Consistent with increased level of SASP-associated GATA4, we observed upregulation of IL-6 at the first two time points and in the primary culture obtained in the progressing tumor." (PMID 29527515, 2018). "Nevertheless, the expression profile of MLL mutated tumor cells and the mechanism of drug-resistant mediated by transcription factors GATA4 and ETS1 should be further identified." (PMID 26625313, 2016). "The results are also coherent with previous findings on high GATA4 or FOXL2 expression in the primary tumor associated with risk of recurrence." (PMID 24416423, 2014). "High-level expression of GATA4 in the primary tumor led to an average threefold increased recurrence risk, independently of tumor stage." (PMID 24687970, 2014). "High-risk tumours according to the PAM classification showed significantly higher GATA-4 expression levels than low-risk tumours (P=0.001)." (PMID 19707195, 2009). "GATA4, although predominantly associated with mesodermal development and regenerative programs, has also shown heterogeneous behavior in cancer biology, acting as either a tumor suppressor or oncogene depending on cellular context." (PMID 41303462, 2025). "Increased GATA-4 expression was associated with advanced tumor stages and risk of tumor recurrence." (PMID 36869369, 2023). "The finding that Gata4 deficiency impacted both tumor burden and tumor initiation are consistent with the hypotheses that Gata4 might operate by regulating cellular proliferation to restrict tumor growth." (PMID 35017504, 2022). "Here we reported a previously unnoticed tumor suppressor enhancing module which could potentially be exploited in clinic for treating GATA4 deficient HCC patients." (PMID 31903133, 2020). "Interestingly, the reciprocal loss of GATA4 or GATA6 in epithelium-derived tumor cells reveals a subsequent loss of Laminin expression." (PMID 31685844, 2019). "Furthermore, we found that high-level expression of HER2 (P = 0.02) and GATA4 (P = 0.006) were associated with tumor recurrence." (PMID 24687970, 2014). "For GATA4, its association with smaller tumor size and overexpression in tumors < 100 mm suggests that it may act as an early-response gene, possibly involved in modulating growth signals or angiogenic responses before morphological dedifferentiation becomes apparent." (PMID 41303462, 2025). "In mouse models, an increased presence of GATA4 slowed down tumor growth, indicating its ability to suppress tumors." (PMID 40699746, 2025). "Numerous studies have shown that promoter hypermethylation (e.g., of GATA4, RASSF1A, CDH1) is closely associated with tumor suppressor gene silencing, tumor progression, and poor prognosis." (PMID 41438986, 2025).
tumor (continued). "It has been shown that GATA4 is found in cancer tissues, and it is correlated with the level of tumor differentiation, indicating a role in cancer progression." (PMID 40699746, 2025). "Specifically, gene expression did not vary significantly with gender (SOX9: p = 0.25; GATA3: p = 0.69; GATA4: p = 0.45), age group (<60 vs. ≥60 years; p range = 0.29–0.87), or tumor site (trunk vs. extremities; p range = 0.38–0.90)." (PMID 41303462, 2025). "A deeper analysis revealed upregulation of genes involved in tumor suppression (Clca2, Spink5, Igfbp6, Nptx1, Bex4, Gadd45g, Yipf5), immune regulation (IL6ra, Ccl6, Cd81, Cd244a, Cd151, and Gata4), apoptosis, and pyroptosis (Ddit3, Rgs6, and Gsdmsc2/3/4)." (PMID 39946195, 2025). "In an in vivo murine breast-cancer model, GATA4 over-expression markedly inhibited metastasis, emphasizing its inhibitory role in tumor invasion." (PMID 41514651, 2025). "GATA4 overexpression correlated with smaller tumor size (<100 mm) (p = 0.049), being more frequent in 15/20 small tumors compared to 10/22 larger ones." (PMID 41303462, 2025). "The results obtained in our study suggest that the tumor expression of the transcription factors GATA4 and GATA6, measured by IHC techniques, is modified throughout tumor development." (PMID 36830789, 2023). "HAND1/2 plays pivotal roles by interacting with Nkx2–5 and GATA4: it encourages proliferation alongside Nkx2–5 and promotes differentiation with GATA4, while also acting as a tumor suppressor (TS)." (PMID 38110859, 2023). "Previous histological analyses described Inha KO tumours as undifferentiated gonadal stromal tumours derived from cells of the Sertoli cell lineage that are positive for GATA4 (Sertoli cell nuclei)." (PMID 37564373, 2023). "While GATA4 expression was reduced during tumor progression, GATA6 expression remained highly conserved, except in lymph node metastases." (PMID 36830789, 2023). "They survive for long periods of time and tightly maintain the gene expression of differentiation genes such as Tbx5, GATA4 that interact with tumor suppressors (TS) and exert TS like effect." (PMID 38110859, 2023). "It should be noted that in PDAC cells, GATA4 plays a role as a differentiation factor and also functions as a tumor suppressor." (PMID 35884771, 2022). "GATA4 is frequently lost in human cancer and our analyses found that GATA4 copy number is positively correlated with the number of TILs in multiple human tumor types." (PMID 35017504, 2022). "Tumor tissue sections were reacted with anti- Tuj1, alpha-smooth muscle, and Gata4 antibodies to examine Okinawa rail, Japanese ptarmigan, and Blakiston’s fish owl-derived tumor tissues." (PMID 36280684, 2022). "To determine if the effects of Gata4 on tumor suppression were dose-dependent, we generated mixed populations with the following percentages of tet-Gata4 cells, with the remaining cells being tet-GFP: 33%, 15%, and 1%." (PMID 35017504, 2022). "Depletion of CD8+ T cells either alone or in combination with CD4+ T cells completely rescued the tumor-suppressive phenotype of Gata4." (PMID 35017504, 2022). "In two independent experiments, mice targeted with sgGata4 exhibited increased tumor burden at 16 weeks when compared to sgCtrl mice, suggesting a Gata4-dependent tumor suppressive phenotype." (PMID 35017504, 2022). "Mechanistically, we show that Gata4-dependent tumor suppression requires cytotoxic CD8 T cells and partially requires the secreted chemokine CCL2." (PMID 35017504, 2022). "Altered expression of GATA4, GATA5, and GATA6 are associated with abroad range of tumours emerging from the gastrointestinal tract, lungs and brain." (PMID 35488350, 2022). "Here, we interrogated the role of GATA4 in tumorigenesis via genetic targeting of Gata4 in multiple in vivo tumor models to clarify its function during tumorigenesis." (PMID 35017504, 2022). "Lastly, we showed that Gata4 overexpression combined with immune checkpoint blockade effectively prevented tumor growth." (PMID 35017504, 2022).